CD151 (CD151 molecule (Raph blood group))
Diseases named in the same sentence as CD151 in open-access papers (continued):
Sharing a sentence is not in itself a finding about the gene and the disease.
glioma (4 papers, 2015 to 2023). A benign or malignant brain and spinal cord tumor that arises from glial cells (astrocytes, oligodendrocytes, ependymal cells). "Recent studies have implicated that FAK is a putative driver of glioma malignancy and acts downstream of CD151-integrin complexes." (PMID 26377974, 2015). "In particular, mutation of IDH1 gene in gliomas has been shown to influence the methylation of a number of pro-malignant genes, and is strongly associated with CD151 expression in our patient cohort." (PMID 26377974, 2015). "Next, analyses of clinical samples were conducted to evaluate the link of CD151-associated α3 integrin to the malignancy of gliomas." (PMID 26377974, 2015). "Together, these data demonstrate a strong association between CD151 expression and glioma aggressiveness." (PMID 26377974, 2015). "Because IDH1 gene status is a powerful prognostic indicator for infiltrative gliomas, we also evaluated the relationship between its mutation status and CD151 expression in our patient cohort." (PMID 26377974, 2015). "In contrast, the migration and invasion of glioma cells are enhanced by the CD151-α3β1 complex, which promotes FAKY397 activation and associated GTPase signaling." (PMID 35280793, 2022). "Together, our analyses of two independent clinical cohorts consistently suggest that CD151 and α3 integrin act together to promote the aggressiveness of gliomas." (PMID 26377974, 2015). "Our analyses of TMA-based glioma patient cohort as well as TCGA glioma dataset consistently indicate that the expression of CD151 or α3β1 integrin is strongly correlated with tumor grade, IDH1 gene status, and patient survival." (PMID 26377974, 2015). "Next, we conducted in vitro analyses to test if CD151 functionally contributed to the aggressiveness of gliomas as suggested by our clinical analyses." (PMID 26377974, 2015). "Our data showed that CD151 was present in the protein complexes of α3 and α6 integrins in multiple glioma cell lines." (PMID 26377974, 2015). "Taken together, these results illustrate that FAK promotes the aggressive traits of gliomas by acting downstream of CD151-integrin complexes and EGFR." (PMID 26377974, 2015). "Meanwhile, there is evidence that CD151 expression in gliomas is regulated by micro-RNAs or epigenetic regulation." (PMID 26377974, 2015). "Additionally, we performed functional studies of multiple glioma cell lines to assess the impact of CD151 ablation on glioma aggressiveness, particularly regarding cell motility and invasiveness." (PMID 26377974, 2015). "In contrast to a prior report on ELMO1, a regulator of GTPase activation and glioma cell motility, our study suggest that the crosstalk between the CD151-integrin complexes and RTKs converge at ARHGAP26, consistent with its link to the EGFR-mediated cell motility and signaling." (PMID 26377974, 2015). "Hence, we examined the signaling link of FAK activation to CD151-integrin complex-mediated glioma aggressiveness." (PMID 26377974, 2015). "Moreover, our data indicate a significant concordance in the expression of CD151 and α3β1 integrin in our patient cohort and TCGA gliomas." (PMID 26377974, 2015). "The contribution of CD151 and associated LB integrins to glioma aggressiveness may not be completely dependent on their crosstalk with the EGFR pathway." (PMID 26377974, 2015). "Thus, there is a likelihood that the aberrant expression of CD151 or α3β1 integrin in high-grade gliomas may result from epigenetic regulation." (PMID 26377974, 2015). "We also analyzed tissue sections from mouse glioma using double-label-immunofluorescence for mouse CD31 and the mouse integrin α3 subunit, integrin α6 subunit, or CD151." (PMID 35879332, 2022). "To evaluate the clinical significance of CD151 in glioma malignancy, we carried out immunohistochemistry (IHC) analyses with a TMA containing 96 paraffin-embedded patient glioma tissues." (PMID 26377974, 2015).
glioma (continued). "However, CD151 knockdown had only minimal effect on the proliferation of glioma cells (data not shown)." (PMID 26377974, 2015).
glomerular disease (4 papers, 2013 to 2025). "The FVB/N strain is known to be highly susceptible to glomerular disease, as demonstrated in Cd151-deficient mice." (PMID 41290692, 2025). "This study provides further evidence that CD151 causes glomerular disease, and we therefore propose that CD151 is included in the panel of genes for investigating glomerular proteinuria." (PMID 35278129, 2022). "In humans and FVB/N mice, loss of functional tetraspanin CD151 is associated with glomerular disease characterised by early onset proteinuria and ultrastructural thickening and splitting of the glomerular basement membrane (GBM)." (PMID 29167507, 2017). "Disruption of the podocyte actin cytoskeleton, signified by effacement of podocyte foot processes, is a major feature of a large number of glomerular pathologies, including glomerular disease associated with CD151 mutations." (PMID 29167507, 2017). "Taken together, these results confirm the patient variant in CD151 is functionally deficient and highlights the use of our zebrafish proteinuria reporter system as a tool for functional analysis of variants associated with glomerular diseases." (PMID 35278129, 2022). "Our results indicate that a novel variant in CD151 is associated with nephrotic-range proteinuria and microscopic haematuria and provides further evidence for a role of CD151 in glomerular disease." (PMID 35278129, 2022). "The down regulation of Scx and Tspan32 genes however occurred in Cd151−/− glomeruli of both strains of mice indicating that it is an effect of Cd151 absence regardless of glomerular disease susceptibility." (PMID 29167507, 2017). "In this regard, comprehensive analysis of single gene disorders and mouse models, such as Cd151 knockout mice, is crucial to a better mechanistic understanding of the tightly orchestrated regulation of glomerular filtration in both normal circumstances and in the context of glomerular disease." (PMID 29167507, 2017). "In glomerular diseases, such as Alport syndrome and diabetic nephropathy, the pathological changes in the GBM result from both altered matrix component synthesis and defective MMP degradation and our results suggest a similar mechanism is occurring in the absence of CD151." (PMID 29167507, 2017).
Alport syndrome (3 papers, 2017 to 2022). A rare renal disease characterized by glomerular nephropathy with hematuria progressing to end-stage renal disease (ESRD), frequently associated with sensorineural deafness, and occasionally with ocular anomalies. "It has been shown that MMP-10 is upregulated as early as 3-weeks in FVB/N CD151-/- mice, suggesting an underlying function of MMP-10 in the early stage of Alport syndrome." (PMID 35216251, 2022). "Interestingly, the GBM abnormalities observed in humans and FVB/N mice lacking CD151 are reminiscent of Alport syndrome, a genetic disorder resulting in an abnormal type IV collagen network and a GBM with laminar or “basketweave” appearance, previously considered unique to this disease." (PMID 29167507, 2017).
COVID-19 (3 papers, 2021 to 2022). A disease caused by infection with severe acute respiratory syndrome coronavirus 2. "CD151 is enriched at the viral entry sites of COVID-19 viruses." (PMID 35629310, 2022). "In terms of immunity, expression changes in CD151, PIDD1, and DPP9—genes involved in immune cell activation and NF-kB-mediated immune response —were associated with two distinct COVID-19 hg-replicated SNPs (rs3934992, rs12610495)." (PMID 34027315, 2021).
epidermolysis bullosa (3 papers, 2014 to 2022). Epidermolysis bullosa (EB) is a group of genetic skin diseases that cause the skin to blister very easily. "Homozygous frameshift and splice site variants in CD151 were associated with epidermolysis bullosa, nail dystrophy and proteinuria leading to kidney failure." (PMID 35278129, 2022).
HCMV infection (3 papers, 2017 to 2022). "The peptide comprising the cytoplasmic C-terminal tail of CD151 significantly reduced HCMV infection rates in EA.hy926 and HEC-LTT cells, while the peptide of the cytoplasmic C-terminal tail of CD63 significantly decreased HCMV infection rates in all cell lines tested." (PMID 30279342, 2018). "More importantly, we show that cytopermeable peptides comprising the C-termini of CD63 and CD151 had a moderate to potent inhibitory effect on HPV16 and HCMV infections in different cell lines." (PMID 30279342, 2018). "We demonstrate that C-terminal peptides of CD63 and CD151 exhibit a moderate to potent inhibitory effect on HPV16 and HCMV infections." (PMID 30279342, 2018). "It has been shown that CD9, CD81 and CD151 were downregulated during HCMV entry and that cellular depletion of CD9, CD63 and CD151 reduced HCMV infection." (PMID 30279342, 2018). "Furthermore, we analyzed the involvement of specific tetraspanin domains, the LEL and the C-terminus, in HPV and HCMV infection by using recombinant peptides or proteins comprising these domains of CD9, CD63, CD81 and CD151 tetraspanins." (PMID 30279342, 2018). "CD81 is a tetraspanin, like CD151 and CD9 that were also downregulated upon HCMV infection." (PMID 29121670, 2017). "In this study we compared the importance of tetraspanins CD9, CD63, CD81 and CD151 in infections by human papilloma- and cytomegalovirus and investigated whether peptides of functional tetraspanin domains could be used as inhibitors of HPV and HCMV infection." (PMID 30279342, 2018).
kidney failure (3 papers, 2014 to 2025). An acute or chronic condition that is characterized by the inability of the kidneys to adequately filter the blood. "This functional importance is highlighted by the phenotypes observed in patients with CD151 mutations or in CD151 knockout (KO) mice, which exhibit conditions similar to integrin deficiencies, such as skin blistering and kidney failure." (PMID 40135387, 2025). "Variants in CD151 have been implicated in nephrotic syndrome, with loss of function variants in humans associated with kidney failure, bullous skin lesions, nail dystrophy and sensorineural deafness." (PMID 35278129, 2022). "Furthermore, treatment of the susceptible Cd151-knockout FVB strain with ACE inhibitors ameliorated progression of renal failure." (PMID 25352829, 2014). "Global deletion of CD151 in mouse models on the FVB background exhibits early, massive proteinuria with associated focal segmental glomerulosclerosis (FSGS) and subsequent kidney failure." (PMID 35278129, 2022). "In mice, deletion of Cd151, both globally and specifically in podocytes, caused early proteinuria with abnormalities of the GBM loss of podocyte foot processes, glomerulosclerosis, loss of podocytes, and renal failure." (PMID 25352829, 2014). "Cd151-knockout mice on the C57BL/6 background do not spontaneously develop renal failure but when challenged with induced hypertension, they develop significant proteinuria." (PMID 25352829, 2014).
metastatic disease (3 papers, 2014 to 2024). "They discovered that patients with metastatic disease or patients with tumors that were highly invasive presented with low expression of CD151." (PMID 34830819, 2021). "The study concluded that low CD151 expression is correlated with metastatic disease." (PMID 34830819, 2021). "Notably, CD151 may be a promising systemic therapeutic strategy that may be useful in metastatic disease, given that targeting this protein has widespread anticancer activity in organs beyond the lungs." (PMID 38982031, 2024).
nephrotic syndrome (3 papers, 2022 to 2024). A collection of symptoms that include severe edema, proteinuria, and hypoalbuminemia; it is indicative of renal dysfunction. "Through targeted NGS, a novel, homozygous truncating variant was identified in CD151, a gene rarely reported in patients with nephrotic syndrome." (PMID 35278129, 2022).
triple-negative breast carcinoma (3 papers, 2012 to 2023). An invasive breast carcinoma which is negative for expression of estrogen receptor (ER), progesterone receptor (PR), and human epidermal growth factor receptor 2 (HER2). "CD151 facilitates secretion of ribosomal proteins while reducing complement proteins to promote the migration and invasion of triple-negative breast cancer cells." (PMID 36941633, 2023). "CD151 expression level in triple-negative breast cancer-derived serum exosomes is significantly higher than those from healthy subjects." (PMID 36941633, 2023). "In the five subtypes analyses, CD151 overexpression retained its adverse impact on OS in the Luminal A (P=0.0105) and quintuple-negative breast cancer (QNBC) subtypes, one subgroup of triple-negative breast cancer (P=0.0170)." (PMID 22294188, 2012).
acute myocardial infarction (2 papers, 2015 to 2018). Necrosis of the myocardium, as a result of interruption of the blood supply to the area. "Our early study showed that CD151 gene delivery after myocardial infarction promoted functional neo-vascularization and activated FAK signaling." (PMID 29581851, 2018). "Recently, it was reported that exogenous CD151 over-expression may promote cardiac angiogenesis and improve cardiac function in rats after acute myocardial infarction." (PMID 29581851, 2018). "The protective effects of CD151 in rats suffering acute myocardial infarction have been reported." (PMID 29581851, 2018). "VEGF expression was detected to elucidate whether VEGF could participate in angiogenesis in the CD151-induced rat myocardial infarction model." (PMID 25452800, 2015).
Alzheimer disease (2 papers, 2023 to 2025). A progressive, neurodegenerative disease characterized by loss of function and death of nerve cells in several areas of the brain leading to loss of cognitive function such as memory and language. "This study probed the effect of targeted regulation of CD151 by microRNA-214-3p (miR-214-3p) delivered by bone marrow mesenchymal stem cells-secreted exosomes (BMSCs-exo) on oxidative stress and apoptosis of neurons in Alzheimer’s disease (AD)." (PMID 40287960, 2025).
asthma (2 papers, 2020). "Furthermore, the prognostic utility of CD151 expression may be extended to other diseases such as asthma, in which the expression of CD151 was associated with disease severity." (PMID 32117989, 2020). "In asthma, CD151 was shown to promote airways hyperresponsiveness through calcium signaling whereas in influenza, CD151 was shown to be a novel host factor for nuclear viral export signaling." (PMID 32117989, 2020). "Expression of CD51 is clinically relevant to asthma as immunohistochemical analysis of human bronchial biopsy specimens for CD151 expression in airway smooth muscle bundles were highest in mild or moderate asthma subjects compared with non-asthmatic subjects." (PMID 32117989, 2020). "What remains to be determined is whether high CD151 expression is a result of asthma or whether elevated expression of CD151 results in asthma." (PMID 32117989, 2020). "Furthermore, the impact of CD151 on the remaining key features of asthma, airway wall remodeling, and airway inflammation, is yet to be established." (PMID 32117989, 2020). "Besides the use of monoclonal antibodies, CD151 gene deletion has been instrumental in improving markers of disease outcomes in asthma, influenza, and tumor progression." (PMID 32117989, 2020). "Also finding that tetraspanin CD151 is upregulated in asthma patients led to discovery that CD151 regulates airway smooth muscle cell contractions mediated by GPCR activation through regulation of intracellular calcium release and its involvement in protein kinase C translocation to the membrane." (PMID 32507938, 2020).
breast tumor (2 papers, 2012 to 2014). "Its association with a larger tumour size in this study can be explained by the previous findings showing that CD151 has a positive role in breast tumour cell growth in vivo, whereas its downregulation causes an inhibition of tumour cell growth." (PMID 22294188, 2012). "However, when we started this work, the possible direct cause-effect relationship between CD151 expression and breast tumor onset/progression and metastasis had never been tested." (PMID 25012362, 2014).
colitis (2 papers, 2018 to 2022). Inflammation of the colon. "Finally, CD151 ablation on T cells was shown to protect mice from experimental colitis, a result confirmed by interruption of CD151:CD151 associations using an antagonistic peptide to the CD151 LEL." (PMID 30072994, 2018). "Moreover, the inhibition of the non-integrin CD151 molecule, which forms a complex with multiple integrins in T cells, resulted in reduced colitis progression in mice." (PMID 35163775, 2022).
focal glomerulosclerosis (2 papers, 2022 to 2024). "Deletion of Cd151 in mice induces glomerular dysfunction, with proteinuria and associated focal glomerulosclerosis, disorganisation of GBM and tubular cystic dilation." (PMID 35278129, 2022). "Interestingly, Daam2 and Cd151 have recently been reported to be upregulated in a dataset of human focal glomerulosclerosis." (PMID 39278930, 2024).
invasive breast carcinoma (2 papers, 2012 to 2024). A carcinoma that infiltrates the breast parenchyma. "Multivariate analysis that included stage, subtype, and adjuvant chemotherapy showed that CD151 overexpression was independently associated with poor OS in invasive breast cancer." (PMID 22294188, 2012). "In particular, high-CD151 expression was significantly correlated with a larger tumour size, higher lymph node involvement, and advanced stage of invasive breast cancer." (PMID 22294188, 2012).
lung adenocarcinoma (2 papers, 2010 to 2015). A carcinoma that arises from the lung and is characterized by the presence of malignant glandular epithelial cells. "In A549 lung adenocarcinoma cells, it has been shown that silencing of CD151 has major effects on downstream tyrosine phosphorylation signaling events involving p130Cas, FAK, paxillin and Src." (PMID 25814554, 2015).
lung diseases (2 papers, 2020). "Developments in the field of nanotechnology and the advent of nanoparticles or nanocarriers in biomedical research provide another avenue for exploiting the importance of CD151 in lung diseases." (PMID 32117989, 2020). "Given the role of CD151 in a milieu of processes that contribute to lung disease pathophysiology, targeting CD151 in a clinical setting is justifiable." (PMID 32117989, 2020). "Potentially the therapeutic targeting of dysregulated Cd151- and Cd9-signaling may contribute to improved and more effective therapy for pulmonary diseases." (PMID 33424923, 2020). "No studies to date have reported the use of CD151-specific binding molecules as a targeting mechanism for drug delivery, but its potential could be explored given the importance of CD151 overexpression in various lung diseases and other human malignancies." (PMID 32117989, 2020). "We also summarize factors that have been shown to regulate CD151 expression and identify key areas that need to be taken into consideration for its utility as a screening or prognostic tool in disease management and/or as a therapeutic target for the treatment of lung diseases." (PMID 32117989, 2020).